NOM1 (nucleolar protein with MIF4G domain 1)
Description:
Plays a role in targeting PPP1CA to the nucleolus.
Synonyms: C7orf3; SGD1; PPP1R113
Tractability: PROTAC: ubiquitination databases record sites on it; its protein half-life has been measured.
Gene: Protein-coding gene on chromosome 7 (156,949,712 to 156,973,176, forward strand). Ensembl gene ENSG00000146909.
Subcellular location: Nucleus, nucleolus
Subcellular location (Human Protein Atlas): Nucleoli
Gene Ontology:
Molecular function: protein binding; RNA binding
Biological process: ribosomal small subunit biogenesis
Cellular component: nucleolus
Genetic constraint (gnomAD): Loss-of-function variants: 51 observed, 67.02 expected, observed/expected ratio (o/e) 0.76, 90% interval 0.61 to 0.96. The upper end of that interval is the gene's LOEUF score, 0.96, which puts it in group 4 of 6, group 1 being the genes least tolerant of losing a copy. Missense variants: 1,190 observed, 1,086.5 expected, observed/expected ratio (o/e) 1.1, 90% interval 1.04 to 1.15. Synonymous variants: 472 observed, 430.3 expected, observed/expected ratio (o/e) 1.1, 90% interval 1.02 to 1.18.
Homologues: Orthologues: chimpanzee NOM1 (98% identical), rabbit NOM1 (81% identical), dog NOM1 (75% identical), pig NOM1 (74% identical), mouse Nom1 (72% identical), rat Nom1 (70% identical), guinea pig NOM1 (69% identical), tropical clawed frog nom1 (56% identical), zebrafish nom1 (52% identical), Drosophila melanogaster CG9004 (31% identical), Caenorhabditis elegans Y52B11A.10 (25% identical). Paralogues in human: CWC22 (16% identical).
Diseases named in the same sentence as NOM1 in open-access papers:
NOM1 is named in the same sentence as 7 diseases in open-access papers, as found by Europe PMC text mining. Sharing a sentence is not in itself a finding about the gene and the disease. The quoted sentences say what the papers report.
leukemia (2 papers, 2021 to 2022). A malignant (clonal) hematologic disorder, involving hematopoietic stem cells and characterized by the presence of primitive or atypical myeloid or lymphoid cells in the bone marrow and the blood. "Here, we tested the expression of Taf1b and Nom1 in normal and leukemia cells following treatment with SD49-7." (PMID 35836814, 2022). "We evaluated the nuclear location of the chromosomal region surrounding MNX1 in the leukemia K562 cell line by FISH, and assessed the transcriptional activity of genes mapping in same region (i.e., LMBR1, NOM1, MNX1, UBE3C, and PTPRN2) by qRT-PCR." (PMID 33652823, 2021). "In this study, we found that the expression of Taf1b and Nom1, downstream of KDM4s, was not affected by SD49-7 in MLL-AF9 GFP+ and THP-1 cells, indicating that KDM4 regulated different downstream genes in leukemia and normal cells." (PMID 35836814, 2022). "However, these inhibitors did not decrease the expression of Taf1b and Nom1 in both MLL-AF9 GFP+ cells and THP-1 cells, indicating that KDM4 regulated different downstream genes in leukemia and normal cells." (PMID 35836814, 2022).
acute myeloid leukemia (1 paper, 2014). Acute myeloid leukemia (AML) is a group of neoplasms arising from precursor cells committed to the myeloid cell-line differentiation. "NOM1 is a nucleolar protein firstly identified from the bone marrow of a pediatric patient with acute myeloid leukemia (AML) carrying a translocation between chromosome 12p13 and 7q36." (PMID 24967912, 2014).
hematological disease (1 paper, 2021). "Genes highlighted here in, such as PRDM16, PER3, NOM1 BAHCC1, ZNF423, SETD7, RPTOR, and others have been implicated in hematological disease development, progression or clinical outcome." (PMID 34200630, 2021).
NOM1 also shares sentences with these, for which no sentence is quoted: Behcet’s syndrome (1 paper); cancer (1); gastric cancer (1); lung agenesis (1).